PPM1A (protein phosphatase, Mg2+/Mn2+ dependent 1A)
Description:
Enzyme with a broad specificity. Negatively regulates TGF-beta signaling through dephosphorylating SMAD2 and SMAD3, resulting in their dissociation from SMAD4, nuclear export of the SMADs and termination of the TGF-beta-mediated signaling. Dephosphorylates PRKAA1 and PRKAA2. Plays an important role in the termination of TNF-mediated NF-kappa-B activation through dephosphorylating and inactivating IKBKB/IKKB.
Synonyms: PP2C-alpha; MGC9201; PP2Calpha; PP2CA
Tractability: Small molecule: it has a high-quality binding pocket. Antibody: its Gene Ontology location is reachable by antibodies, with high confidence. PROTAC: ubiquitination databases record sites on it; its protein half-life has been measured; a small molecule that binds it is known.
Target class: Protein Phosphatase; Phosphatase; Serine/threonine protein phosphatase; Enzyme
Gene: Protein-coding gene on chromosome 14 (60,245,752 to 60,299,089, forward strand). Ensembl gene ENSG00000100614.
Subcellular location: Nucleus; Cytoplasm, cytosol; Membrane
Subcellular location (Human Protein Atlas): Cytosol; Plasma membrane
Pathways (Reactome):
Signal Transduction: Downregulation of SMAD2/3:SMAD4 transcriptional activity; Energy dependent regulation of mTOR by LKB1-AMPK
Gene Ontology:
Molecular function: calmodulin-dependent protein phosphatase activity; protein binding; protein serine/threonine phosphatase activity; R-SMAD binding; cation binding; magnesium ion binding; manganese ion binding; phosphoprotein phosphatase activity
Biological process: negative regulation of canonical NF-kappaB signal transduction; negative regulation of non-canonical NF-kappaB signal transduction; negative regulation of transforming growth factor beta receptor signaling pathway; positive regulation of canonical NF-kappaB signal transduction; positive regulation of canonical Wnt signaling pathway; positive regulation of DNA-templated transcription; protein dephosphorylation; N-terminal protein myristoylation; negative regulation of transcription by RNA polymerase II; regulation of canonical NF-kappaB signal transduction; regulation of cell cycle
Cellular component: cytosol; membrane; nucleus; nucleoplasm
Genetic constraint (gnomAD): Loss-of-function variants: 5 observed, 27.68 expected, observed/expected ratio (o/e) 0.18, 90% interval 0.093 to 0.38. The upper end of that interval is the gene's LOEUF score, 0.38, which puts it in group 1 of 6, group 1 being the genes least tolerant of losing a copy. Missense variants: 205 observed, 441.79 expected, observed/expected ratio (o/e) 0.46, 90% interval 0.41 to 0.52. Synonymous variants: 138 observed, 159.55 expected, observed/expected ratio (o/e) 0.86, 90% interval 0.75 to 1.
Homologues: Orthologues: chimpanzee PPM1A (100% identical), macaque PPM1A (100% identical), dog PPM1A (99% identical), guinea pig PPM1A (99% identical), rat Ppm1a (99% identical), mouse Ppm1a (98% identical), rabbit PPM1A (98% identical), pig PPM1A (97% identical), tropical clawed frog ppm1a (91% identical), zebrafish ppm1aa (84% identical), zebrafish ppm1ab (71% identical), Drosophila melanogaster CG10376 (22% identical), and 2 more. Paralogues in human: PPM1B (76% identical), PPM1N (43% identical), PPM1G (32% identical), PPM1D (29% identical), PPM1E (26% identical), PPM1H (24% identical), PPM1K (24% identical), ILKAP (23% identical), PDP1 (23% identical), PPM1F (23% identical), PPM1L (21% identical), PPM1J (21% identical), and 4 more.
Diseases named in the same sentence as PPM1A in open-access papers:
PPM1A is named in the same sentence as 55 diseases in open-access papers, as found by Europe PMC text mining. Sharing a sentence is not in itself a finding about the gene and the disease. The quoted sentences say what the papers report.
bladder cancer (7 papers, 2014 to 2023). "PPM1A deficiency is apparent in bladder cancer correlating with SMAD2/3 activation, muscular invasion and poor outcomes." (PMID 29799477, 2018). "In metastatic bladder cancer, loss of PPM1A expression significantly promoted urinary bladder cancer cell motility, EMT in vitro, and metastasis in vivo, which were dependent on the TGF-β/smad signaling pathway." (PMID 28283039, 2017). "We evaluated the expression status of PPM1A in BCa tissue samples and found that PPM1A is a prognostic factor that is especially associated with the development of tumor invasion in bladder cancer patients." (PMID 25026293, 2014). "PPM1A was more commonly deficient among muscle-invasive relapse samples compared to primary tumors in twenty paired bladder cancer tissues." (PMID 25026293, 2014). "Stable silencing of PPM1A in T4 and 5637 bladder cancer cells, in fact, promoted EMT/epithelial plasticity in response to TGF-β1 while increasing tumor growth and metastasis." (PMID 29799477, 2018). "In previous studies, PPM1a down-regulation leads to a dramatic promotion on migration and invasiveness of bladder cancer, while inhibitors of TβRI (SB431542) treatment markedly abolished this effect." (PMID 27121309, 2016). "Both in bladder cancer and metastatic prostate cancer, expression of PPM1a decreases and negatively correlates with the histological grade, metastasis and survival time of the patients." (PMID 27121309, 2016). "In this study, we investigated the role of PPM1A in bladder cancer." (PMID 25026293, 2014). "Furthermore, 20 matched pairs of primary tumors and recurrent bladder cancer samples were analyzed for PPM1A protein expression." (PMID 25026293, 2014). "Functional studies indicated that blockade of PPM1A through lentivirus-mediated RNA interference significantly promoted urinary bladder cancer (BCa) cell motility, the EMT in vitro and metastasis in vivo, and these effects were dependent on the TGF-β/Smad signaling pathway." (PMID 25026293, 2014). "PPM1A protein expression was analyzed in 145 bladder cancer specimens." (PMID 25026293, 2014). "Previous publications have reported that PPM1A modulates TGF-β signaling by dephosphorylating and inactivating SMAD2 in epithelial cell, keratinocyte, and bladder cancer cells." (PMID 36752205, 2023). "PPM1A down-regulation increased epithelial-to-mesenchymal transition (EMT) progress and invasion through increasing the activity of Smad2/3 signaling pathway in bladder cancer." (PMID 29898761, 2018).
hepatocellular carcinoma (6 papers, 2016 to 2025). A malignant tumor that arises from hepatocytes. "For instance, the Dual-Luciferase® Reporter Assay has been successfully applied in hepatocellular carcinoma to confirm the regulation of PPM1A by HBV-miR-3." (PMID 40559621, 2025). "PPM1A expression is significantly downregulated in human hepatitis C virus (HCV)-related hepatocellular carcinomas (HCC) compared to normal liver tissues." (PMID 29799477, 2018). "The mechanism by which NS3 downregulates PPM1A abundance was revealed, and the roles of PPM1A in regulating hepatoma cell invasion and migration were assessed in vitro." (PMID 28283039, 2017). "Together, these results provided strong evidence that PPM1A is downregulated in HCV-infected hepatoma cells." (PMID 28283039, 2017). "In this study, we found that PPM1A was strongly downregulated and its normal nuclear localization shifted to a mainly cytoplasmic distribution following infection of cultured hepatoma cells with HCV." (PMID 28283039, 2017). "Expression of PPM1A is notably reduced in tumor tissues of hepatocellular carcinoma (HCC)." (PMID 40141322, 2025). "Finally, the roles of NS3 and PPM1A in hepatoma cell migration and invasion were assessed by wound healing and transwell assays, respectively." (PMID 28283039, 2017). "Next, we tried to explore how HBx down-regulates PPM1a in hepatoma cells." (PMID 27121309, 2016). "Our findings demonstrate that the HCV protein NS3 can downregulate PPM1A by promoting its ubiquitination and proteasomal degradation, which might contribute to the migration and invasion of hepatoma cells and may represent a new strategy of HCV in carcinogenesis." (PMID 28283039, 2017). "HCV infection and replication decreased PPM1A abundance, mediated by NS3, in hepatoma cells." (PMID 28283039, 2017).
viral infection (5 papers, 2012 to 2023). "Third, TRIM18 promotes the stability of PPM1A by inducing its K-63 linked polyubiquitination during virus infection." (PMID 35909127, 2022). "Particularly, Ppm1a–/—MEFs also exhibited reduced viral replication after HSV-1 or VSVΔM51-GFP virus infection, demonstrating its biological importance." (PMID 25815785, 2015). "We found that overexpression of PPM1A inhibits HIV-1 gene expression during viral infection and this required PPM1A catalytic function." (PMID 22727189, 2012). "Interestingly, we found that viral infection could increase the association between PPM1A and STING, since an apparent elevation of PPM1A levels were detected in the STING immunoprecipitates at the 8-hour time point post-HSV-1-infection." (PMID 25815785, 2015). "Another E3 ubiquitin ligase TRIM18 recruited protein phosphatase 1A (PPM1A), a negative regulator of STAT1, to dampen type I interferon-mediated antiviral innate immunity for promoting virus infection." (PMID 36817462, 2023). "Collectively, these data suggest that TRIM18 recruits PPM1A to dephosphorylate TBK1 for its inactivation and blocks interaction of TBK1 with its upstream adaptors MAVS and STING for signal transduction during virus infection." (PMID 35909127, 2022). "TRIM18 was shown to recruit protein phosphatase 1A (PPM1A) to dephosphorylate TBK1, which inactivates TBK1 and blocks its interactions with upstream adaptors MAVS and STING, thereby dampening type I IFN mediated antiviral signaling during viral infections." (PMID 35909127, 2022). "Importantly, we detect interaction of TRIM18 with both PPM1A and TBK1 after virus infection, which drove us to further investigate the molecular mechanisms by which TRIM18 targets TBK1 to dampen type I IFN production in virus infection." (PMID 35909127, 2022). "Mechanistically, we demonstrated that TRIM18 recruited the protein phosphatase PPM1A to dephosphorylate TBK1, which inactivated TBK1 and blocked interactions of TBK1 with its upstream adaptors MAVS and STING, dampening type I IFN mediated antiviral signaling during virus infection." (PMID 35909127, 2022). "However, a possible regulation of PPM1A expression by viral infection was not examined in this study." (PMID 27004401, 2016).
ankylosing spondylitis (4 papers, 2020 to 2024). An autoimmune chronic inflammatory disorder characterized by inflammation in the vertebral joints of the spine and sacroiliac joints. "Protein phosphatase magnesium‐dependent 1A (PPM1A), serine/threonine protein phosphatase, in sera level was increased in patients with ankylosing spondylitis (AS)." (PMID 36756789, 2023). "In contrast, using an array of 8087 human proteins, an anti-PPM1A autoantibody was discovered in ankylosing spondylitis that was not present in rheumatoid arthritis." (PMID 39449329, 2024).
breast carcinoma (4 papers, 2019 to 2024). "Overall, this study demonstrates PPM1A is frequently deleted in ER-negative breast cancers, and that loss of PPM1A promotes the growth of TNBCs, suggesting that PPM1A is an important tumor suppressive gene in these aggressive breast cancers." (PMID 31372497, 2019). "An analysis comparing RNA levels across breast cancer subtypes revealed that PPM1A is underexpressed in TNBC cells, and this downregulation was associated with TNBC growth." (PMID 38473804, 2024). "To investigate the role of PPM1A in regulating breast cancer survival and growth, we first compared PPM1A protein levels in ER-positive and ER-negative breast cancer cell lines, and an immortalized normal breast cell line." (PMID 31372497, 2019). "Our results demonstrate PPM1A is deleted frequently in breast cancer, is underexpressed in TNBCs, and that overexpression of PPM1A reduces TNBC tumor growth." (PMID 31372497, 2019). "To study the role of PPM1A in the regulation of breast cancer cell growth, we cloned PPM1A cDNA into a tetracycline (Tet)-inducible vector (pTIPZ)." (PMID 31372497, 2019). "Our results, reflecting three independent experiments, show that induced expression of PPM1A arrests breast cancer cells in G0/G1 phase and prevents S-phase entry." (PMID 31372497, 2019). "In this study we investigated the role of PPM1A, a phosphatase underexpressed in ER-negative as compared to ER-positive breast cancers, in the regulation of breast cancer growth." (PMID 31372497, 2019). "Our results demonstrate that PPM1A expression was significantly induced in the breast cancer cell lines after 4 days of doxycycline treatment." (PMID 31372497, 2019). "The ability of ER-positive breast cancers to grow, even in the presence of high levels of PPM1A suggests that in these cancers rely on other pathways, such as those stimulated by the estrogen and the estrogen receptor, support unregulated growth in ER-positive breast cancers." (PMID 31372497, 2019). "Interestingly, protein abundance of HPRT1, HNRNPA0, IFIT3, CTNND1 and EIF4A3 predicted poor overall survival in breast cancer patients, however, PPM1A association was non-significant." (PMID 32532008, 2020). "Mechanistic studies showed that induced PPM1A blocks the cell cycle of ER-negative cells at the G1/S and inhibits CDK and Rb phosphorylation, which results in the arrest of breast cancer cell growth." (PMID 31372497, 2019). "We next used cell counting to determine the effect of PPM1A on breast cancer cell growth with and without doxycycline treatment." (PMID 31372497, 2019). "Taken together, these results demonstrate that induction of PPM1A inhibits proliferation of ER-negative, but not ER-positive, breast cancer cells." (PMID 31372497, 2019). "Our results indicate induced expression of PPM1A can strongly suppress cell growth of the PPM1A-transfected ER-negative cell lines tested (SUM159: 73% repression; MDA-MB-231: 59% repression), but does not suppress growth in PPM1A-transfected ER-positive (MCF7) breast cancer cells (respectively)." (PMID 31372497, 2019).
HIV-1 infection (4 papers, 2012 to 2018). The type species of lentivirus and the etiologic agent of acquired immunodeficiency syndrome (AIDS). "In this study, the authors showed that increased PPM1A expression rendered macrophages highly susceptible to HIV-1 infection, while depletion of PPM1A rendered them relatively resistant to HIV-1 infection." (PMID 28276468, 2017). "PPM1A up-regulation rendered macrophages highly susceptible to HIV-1 infection, and inert to bacterial stimuli." (PMID 27004401, 2016). "Titration of HIV-1 WEAU, a clinical HIV-1 isolate derived from a patient during acute infection, on either THP-1 cells or THP-PPM1A cells confirmed that PPM1A overexpression rendered macrophages more susceptible to HIV-1 infection." (PMID 27004401, 2016). "Conversely, knockdown of PPM1A expression reduced the susceptibility of macrophages to HIV-1 infection." (PMID 27004401, 2016). "Genetic manipulation studies revealed that increased PPMA1 expression rendered THP-1 cells highly susceptible to HIV-1 infection, while depletion of PPM1A rendered them relatively resistant to HIV-1 infection." (PMID 27004401, 2016). "The results confirmed our initial findings in THP-1 cells and clearly demonstrated that PPM1A expression rendered macrophages more susceptible to HIV-1 infection." (PMID 27004401, 2016). "We have previously reported that both M. tuberculosis and HIV-1 infection of macrophages induces increased PPM1A expression." (PMID 29343725, 2018). "In macrophages, both Mtb and HIV-1 infection induced higher level of expression of PPM1A in favor to the infection." (PMID 28276468, 2017). "Accordingly, knockdown of PPM1A expression allowed the cellular innate antiviral response of macrophages to better control HIV-1 infection." (PMID 27004401, 2016). "It is also important to note that PPM1A must play a completely different role in HIV-1 infection of macrophages and T cells." (PMID 27004401, 2016). "A particularly interesting aspect of the presented data is that HIV-1 infection by itself increased PPM1A expression levels." (PMID 27004401, 2016). "To exclude the possibility that PPM1A would control macrophage susceptibility to HIV-1 infection by affecting HIV-1 LTR promoter activity, we assessed the effect of PPM1A on Tat-dependent or independent HIV-1 LTR activity." (PMID 27004401, 2016). "Seeking to identify biomolecular processes that would link Mtb and HIV-1 infection at the interface of their common host cell, we sought to further investigate a possible role for PPM1A expression in the context of Mtb and HIV-1 co-infection." (PMID 27004401, 2016). "We further show that HIV-1 infection of macrophages directly up-regulated PPM1A expression, suggesting that virus-mediated PPM1A up-regulation would be a previously undescribed viral escape mechanism." (PMID 27004401, 2016). "Mtb infection-induced PPM1A up-regulation in macrophages would act to undermine a cellular antiviral defense mechanism to boost HIV-1 infection." (PMID 27004401, 2016). "The role of PPM1A in the context of HIV-1 infection had previously been studied in T cells, where PPM1A expression was found to inhibit HIV-1 expression." (PMID 27004401, 2016). "We demonstrate that both Mtb and HIV-1 infection induce the expression of PPM1A in primary human monocyte/macrophages and THP-1 cells." (PMID 27004401, 2016). "Conversely, up-regulation of PPM1A expression in response to HIV-1 infection would be detrimental for the antibacterial response to Mtb infection." (PMID 27004401, 2016). "In this study, we therefore wanted to examine the effect of PPM1A overexpression on HIV-1 infection and gene expression." (PMID 22727189, 2012). "PPM1A had been previously investigated for a potential role in HIV-1 infection of T cells." (PMID 27004401, 2016).
HIV-1 infection (continued). "If up-regulation of PPM1A could undermine the antiviral defense against HIV-1 infection, we reasoned that depletion of PPM1A would result in an opposing effect and would reduce macrophage susceptibility to HIV-1 infection." (PMID 27004401, 2016). "We thus next investigated whether HIV-1 infection would directly alter PPM1A expression in macrophages." (PMID 27004401, 2016). "Our data suggest that inhibition of PPM1A could prevent or reverse the establishment of persistent Mtb infection and simultaneously inhibit HIV-1 infection of macrophages." (PMID 27004401, 2016). "We found that overexpression of PPM1A inhibits HIV-1 infection and gene expression." (PMID 22727189, 2012). "As our HIV-1 infection data in PPM1A overexpressing THP-1 cells suggest that PPM1A up-regulation is likely to interfere with viral silencing mechanisms, HIV-1 may have indeed evolved to undermine a cellular innate antiviral mechanism in an attempt to counteract viral silencing." (PMID 27004401, 2016). "Here, we demonstrate how Mtb infection boosted the expression of Protein Phosphatase, Mg2+/Mn2+ Dependent 1A (PPM1A) in macrophages, a phenotype that undermined the intrinsic antiviral cellular response to promote HIV-1 infection." (PMID 27004401, 2016). "If PPM1A would act to disable the cellular innate antiviral response in a manner similar to its role in HSV infection, we would expect to see a post-entry effect on HIV-1 infection." (PMID 27004401, 2016). "We confirm this finding and demonstrate that PPM1A levels in T cells are also not regulated by HIV-1 infection." (PMID 27004401, 2016). "While we confirm that T cells express high baseline levels of PPM1A and demonstrate that HIV-1 infection does not affect PPM1A expression levels in T cells, we find relatively low basal levels of PPM1A in monocytes, which are then up-regulated upon infection by Mtb or HIV-1." (PMID 27004401, 2016). "Given the reported link between PPM1A levels and the antiviral response in HSV infection, we next tested whether PPM1A up-regulation in monocytes/macrophages, as induced by Mtb infection, would actually affect HIV-1 infection." (PMID 27004401, 2016).